ATP7B (ATPase copper transporting beta)
Diseases named in the same sentence as ATP7B in open-access papers (continued):
Sharing a sentence is not in itself a finding about the gene and the disease.
cancer (continued). "As we know, ATP7A is correlated with cisplatin resistance in different cancers, and similar to ATP7A, ATP7B mediates resistance to cisplatin in various tumors." (PMID 32508020, 2020). "We previously reported that ATP7B is involved in cisplatin resistance and ATP7A confers multidrug resistance (MDR) in cancer cells." (PMID 26988911, 2016). "Cisplatin, a platinum-containing anti-cancer drug, binds to copper sites of ATP7A and ATP7B, and undergoes vectorial displacement in analogy with copper." (PMID 25242165, 2014). "In contrast, protein expression of ATP7b (copper transporter ATP7b), mRNA expression of ABCG2 (BCRP, breast cancer resistance protein), ABCC2 (MRP2), and SLC31A1 (hCTR1, human copper transporter 1) did not correlate with survival." (PMID 25275603, 2014). "In malignant tumors, high expression of ATP7A or ATP7B increases cisplatin resistance." (PMID 40316883, 2025). "Furthermore, TM can counteract chemotherapy resistance, which some cancer cells develop through increased expression of copper transport proteins (e.g., ATP7A and ATP7B)." (PMID 40406488, 2025). "In addation, CAT, POLE, NTHL1, ATP7B, ISCA2, NDUFA1 and NDUFB2 have also been reported to play a key role in the development of cancers." (PMID 36685880, 2022). "Moreover, compared with other CGRs, ATP7B, NLRP3, and ATP7A are significantly hypomethylated in various cancers, such as BRCA, LUSC, and LUAD." (PMID 36387247, 2022). "On the contrary, KIRCs were found to potentially have a lower copper cell death in cancer tissue because their anti-cuproptosis gene ATP7B was upregulated with pro-copper metabolism-related cell death genes SLC31A1, FDX1, DLAT, and LIAS downregulated in cancer tissues." (PMID 36276096, 2022). "Results showed that the cancer–noncancer protein expression patterns of ATP7B, SLC31A1, DLAT, and LIAS were mostly consistent with the patterns at the mRNA level but that of FDX1 was not." (PMID 36276096, 2022). "For example, the expression of DLAT, LIAS, and ATP7B was negatively correlated with the methylation in most of the cancer types, while the expression of SLC31A and FDX1 was not remarkably correlated with the methylation in most of the cancer types." (PMID 36276096, 2022). "The cuproptosis inhibitory genes, ATP7B and ATP7A, as well as the remaining cuproptosis promoting CuRGs, are highly heterogeneous in tumors but tend to be lowly expressed, which may suggest a lower activation level of cuproptosis in cancer patients." (PMID 38573998, 2024). "Although the ability of ATP7B to counteract metal toxicity is essential for the homeostasis of liver tissue, such ATP7B ability might play a negative role in cancer." (PMID 35053335, 2022). "ATP7B and NLRP3 showed a negative correlation in most cancers (P < 0.05)." (PMID 36387247, 2022). "We also found that ATP7B and MSI showed significant positive correlations in 5 of 33 common cancers, including CHOL, ESCA, LGG, LUAD, LUSC, while ATP7B showed significant negative correlations with MSI in 7 of 33 cancers, including BRCA, COAD, DLBC, HNSC, READ, TGCT, THCA." (PMID 38037104, 2023).
genetic disorder (23 papers, 2013 to 2026). "This further confirms that the mutation at this site in the ATP7B gene indeed causes splicing abnormalities, leading to a genetic disease." (PMID 40557282, 2025). "WD is a genetic disorder resulting from mutations in the ATP7B gene, exhibiting significant genetic heterogeneity with over 600 mutations or polymorphisms." (PMID 39854622, 2024). "Genetic disorders of ATP7B cause excess Cu and trigger the pathogenesis of Wilson disease, whereas genetic disorders of ATP7A cause Cu deficiency in Menkes disease." (PMID 39062487, 2024). "The dysfunction of ATP7B contributes to WD, an autosomal recessive genetic disorder of copper metabolism caused by a mutation in the ATP7B gene." (PMID 29358698, 2018). "This provides theoretical support for diagnosing and preventing the occurrence of related diseases, expands the spectrum of pathogenic mutations in the ATP7B gene, and offers theoretical support and research ideas for future studies on related genetic diseases." (PMID 40557282, 2025). "WD is a genetic disorder of copper metabolism caused by mutations in the ATP7B gene." (PMID 38928192, 2024). "Genetic diseases are caused by impaired Cu transporters CTR1, ATP7A, or ATP7B but little is known about the regulatory mechanisms by which these proteins meet the fluctuating demands of Cu in specific tissues." (PMID 37391383, 2023). "Based on results showing abnormal copper metabolism, corneal Kayser–Fleischer rings, and genetic disorders in the ATP7B gene, the patient was finally diagnosed with WD." (PMID 34666712, 2021). "Genetic disorders of the ATP7B gene disrupt the synthesis and function of the ATP7B protein, and further impair the copper excretion pathway, leading to the abnormal deposition of copper in the body." (PMID 34470610, 2021). "This enables zinc to bind excess copper, which avoids genetic disorders and releases oncogenic enzymes, such as ATP7A, ATP7B, CTR1, and ATOX1, to regulate homeostasis." (PMID 37049685, 2023).
metabolic disease (10 papers, 2019 to 2025). A congenital disorder (due to inherited enzyme abnormality) or acquired (due to failure of a metabolically important organ) disorder resulting from an abnormal metabolic process. "Wilson's disease (WD) is an inherited metabolic disease culminating in pathological progressive copper accumulation in the liver and other tissues and is known to be caused by a genetic defect in the ATPase copper transporting beta gene (ATP7B)." (PMID 37362448, 2023). "The metabolic disorder caused by ATP7B variants can result in multiple organ and multisystem damage, and delayed diagnosis and treatment of the disease results in poor patient prognosis." (PMID 34240825, 2021). "Wilson’s disease (WD) is an inherited metabolic disease arising from ATPase copper transporting beta gene (ATP7B) mutation." (PMID 30733544, 2019).
brain disease (2 papers, 2023 to 2025). "The exact mechanism linking brain disease, elevated copper levels, and neuronal dysfunction with ATP7B expression is unclear to date." (PMID 40955271, 2025).
kidney disorder (2 papers, 2023). A disease involving the kidney. "The genetic defect in ATP7B usually results in liver injury and neuropsychiatric involvement, while kidney disease is a presenting feature in only approximately 1% of patients." (PMID 37681011, 2023).
infection (1 paper, 2016). The state of being infected such as from the introduction of a foreign agent such as serum, vaccine, antigenic substance or organism. "Furthermore, the abundance of ATP7B progressively increased in both the renal cortex and medulla during infection, but its subcellular localisation remained unchanged over the course of the disease." (PMID 27362522, 2016). "Therefore, we compared renal ceruloplasmin, CTR1, ATP7A and ATP7B protein levels in animals at different stages of infection." (PMID 27362522, 2016). "We observed no change in the subcellular localisation of ATP7B, which was detected as defined punctate structures at each infection stage." (PMID 27362522, 2016). "However, we did observe a gradual decrease in ATP7B levels in the splenic red pulp, suggesting quantitative rather than qualitative effects of infection on ATP7B." (PMID 27362522, 2016).
movement disorder (1 paper, 2025). Neurological conditions resulting in abnormal voluntary or involuntary movement, which may impact the speed, fluency, quality and ease of movement. "Clinicians should complete ceruloplasmin, 24-h urinary copper, and ATP7B genetic testing in patients with movement disorders and claustrum sign." (PMID 40496135, 2025).
ATP7B also shares sentences with these, for which no sentence is quoted: phenylketonuria (6 papers); Parkinsonism (5); cystic fibrosis (4); neurological disease (4); autosomal-recessive hereditary disease (3); hemochromatosis (3); adenocarcinoma (2); head and neck cancer (2); Krabbe disease (2); occipital horn syndrome (2); polyposis (2); spinal muscular atrophy (2); thalassemia (2); 5-alpha reductase deficiency (1); Acute hepatitis (1); alpha 1-antitrypsin deficiency (1); Alpha-thalassemia (1); angiomyolipoma (1); Arthritis (1); asthma (1); Ataxia (1); atherosclerosis (1); auditory neuropathy (1); autosomal recessive polycystic kidney disease (1); beta thalassemia (1); biotinidase deficiency (1); bone cancer (1); carnitine deficiency (1); Charcot-Marie-Tooth disease type (1); Chorea (1).
A further 85 diseases each share a sentence with ATP7B in 1 paper.